COL5A1 (collagen type V alpha 1 chain)
Diseases named in the same sentence as COL5A1 in open-access papers (continued):
Sharing a sentence is not in itself a finding about the gene and the disease.
cancer (73 papers, 2013 to 2026). A tumor composed of atypical neoplastic, often pleomorphic cells that invade other tissues. "A previous study shows that COL5A1 was a cancer-associated fibroblast gene signature as a poor prognostic factor and potential therapeutic target in GC48." (PMID 40386054, 2025). "We discovered that three cancer hallmark gene sets, i.e. apical junction, coagulation, and complement system (part of the innate immune system), were significantly enriched in COL5A1 neighboring genes." (PMID 37862225, 2023). "The results elucidated that COL5A1 expression positively related to immune scores in 19 cancers but negatively associated with immune scores in TGCTs." (PMID 35082969, 2022). "Herein, we aimed to assess the prognostic value of COL5A1 in 33 human cancers and to investigate its underlying immunological function." (PMID 35082969, 2022). "COL3A1 and COL5A1 are functionally related in connective tissue disorders, and expression of different collagens are associated with various cancers." (PMID 23383328, 2013). "COL5A1 depicted a positive association with M2 macrophages and cancer-associated fibroblasts." (PMID 38610959, 2024). "To date, COL5A1 has also been implicated as an oncogenic protein in the central nervous system and in gastric, ovarian, breast, and many other cancers, being negatively related to the prognosis of 11 cancers." (PMID 37174662, 2023). "We also found that COL5A1 genetic variants existed in multiple cancer types." (PMID 35082969, 2022). "The highest expression of genes encoding Col1a1-2, Col3a1, Col4a1, Col4a2, Col5a1, Col5a2, Col6a1, Col8a1, Col9a3, Col10a1, Col12a1, Col14a1, Col15a1, Col16a1, Col18a1, and Col28a1 were detected in untreated tumors, whose landscapes were dominated by Krt8+ cancer cells." (PMID 39372930, 2024). "Additionally, COL5A1 expression was positively linked to stromal scores in 30 human cancers." (PMID 35082969, 2022). "Furthermore, COL5A1 was a high-risk gene in these cancers, particularly UVM (hazard ratio = 2.426)." (PMID 35082969, 2022). "Many hypoxia-upregulated genes, including COL1A1, COL5A1, COL6A3, LAMC2, and SERPINE1, are linked to enhanced migration, invasion, immune evasion, or treatment resistance in various cancers, including NSCLC." (PMID 41009714, 2025). "Altogether, these findings indicate that P4HA2 regulates autophagy activity to control the proteostasis of COL5A1, ultimately influencing the dormant state of cancer cells." (PMID 40671813, 2025). "DNA methylation had a moderate contribution for the two newly predicted cancer genes, COL5A1 and MSLN." (PMID 37862225, 2023). "Particularly, the positive correlations of PODNL1 expressions with such collagens as collagen type 1 alpha 1 chain (COL1A1), COL1A2 and collagen type V alpha 1 chain (COL5A1) were found in over 30 types of cancers." (PMID 37504302, 2023). "Some ECM structural proteins, including Col5A1 and Col15A1, were downregulated in the cancer-conditioned fibroblasts in our cell culture experiments." (PMID 37903851, 2023). "We identified 25 genes that are highly correlated (rho ≥ 0.5) with both COL1A1 and COL5A1 in all three cancers." (PMID 35739492, 2022). "Survival analyses, including OS, DSS, DFI, and PFI, were carried out for patients with 33 cancers to investigate the correlation between COL5A1 expression and prognosis." (PMID 35082969, 2022). "The heat map demonstrated that most immune-related genes were coexpressed with COL5A1, and major immune activation, chemokine, and chemokine receptor genes exhibited a positive correlation with COL5A1 expression in major cancers." (PMID 35082969, 2022). "We analyzed the RNA sequencing data from TCGA through using the R software to further evaluate the expression of COL5A1 in different cancers." (PMID 35082969, 2022).
cancer (continued). "Presently, very few works have assessed the immunological action of COL5A1 in cancers, and COL5A1 is commonly presumed to be a collagen family protein (the most abundant matrix protein polymer in vertebrates) that is involved in the formation of ECM." (PMID 35082969, 2022). "This first pan-cancer analysis of COL5A1 showed high COL5A1 expression in most tumors compared with normal tissues and revealed a correlation between COL5A1 expression and the prognosis." (PMID 35082969, 2022). "Among them, collagen family Col1a1, Col4a2 and Col5a1 are target genes of miR-29a-3p, and promote cancer cells invasion and migration." (PMID 34135859, 2021). "All this evidence indicates that COL5A1 plays a dominant role in the composition of fibrous collagen, extracellular matrix remodeling and the cancer microenvironment." (PMID 34702798, 2021). "In the present study, we validated six direct targets of EZH2 that are GPNMB, PMEPA1, CoL5A1, VGLL4, POMT2 and SUMF1 associated with cancer related pathways." (PMID 30760814, 2019). "Of the other 16 genes, COL5A1, GABBR1, HACE1, EPHA7, and TRIP11 have well-documented associations with cancer." (PMID 30962767, 2019). "COL5A1 is a NCG cancer gene acting as a minor connective tissue component of nearly ubiquitous distribution." (PMID 28415609, 2017). "Additionally, we also found in various cancer types several other prognostic pairs potentially associated with intercellular communications such as the recurrent interactions between miR-532-5p and COL5A1 (prognostically promising in KIRC and LGG) and between miR-1307-3p and ST6GALNAC6." (PMID 25403569, 2014). "The newly predicted cancer gene COL5A1 combined information from all six PPI networks." (PMID 37862225, 2023). "As a case study, we analysed the predictions of a newly predicted cancer gene, COL5A1." (PMID 37862225, 2023). "EMGNN predicted COL5A1 as a cancer gene with high confidence." (PMID 37862225, 2023). "Identifying the players for the opposing roles of COL1A1 and COL5A1 in different cancers could reveal new insights into the field." (PMID 35739492, 2022). "COL5A1 expression was related to the TMB in 13 cancer types." (PMID 35082969, 2022). "In our study, COL5A1 played a critical role in the cancer immunity." (PMID 35082969, 2022). "Therefore, an investigation of the relationships between the TMB and COL5A1 across cancers is necessary." (PMID 35082969, 2022). "The correlation between COL5A1 and drug sensitivity was found in several cancers." (PMID 35082969, 2022). "The data illustrated that COL5A1 regulated some immune-related functions in 18 cancer types." (PMID 35082969, 2022). "Additionally, DNA methylation of COL5A1 was increased in several cancers and affected the survival of patients." (PMID 35082969, 2022). "We further investigated the DNA methylation levels of COL5A1 in 33 cancer types." (PMID 35082969, 2022). "We also identified different roles for COL5A1 in the immunocyte infiltration in different cancers." (PMID 35082969, 2022). "Meanwhile, we assessed the mRNA sequence of COL5A1 in 33 cancers in the CCLE database." (PMID 35082969, 2022). "Recent studies have found that COL5A1 may be related to the occurrence and progression of several types of malignant tumors." (PMID 34702798, 2021). "Since K69 and K285 residues are known regulatory switches for DVL-1 nuclear localization, we wanted to determine whether these K-residues on DVL-1 also influence transcript levels of DVL-1 target genes such as TRIO, COL5A1 and EXD3 implicated in cancer." (PMID 34659647, 2021). "Therefore, our database-based pan-cancer analysis suggests that these four collagen family genes (COL5A1, COL3A1, COL4A1, and COL15A1) have commonality with the progression of various tumors." (PMID 34691289, 2021). "Accumulating researches indicated that COL5A1 might be a new prognostic candidate for many carcinomas." (PMID 34026819, 2021).
cancer (continued). "Finally, both CRP and FFV PEVs significantly upregulated gene expression of ECM components (e.g. MMP14, MMP16, collagen type V alpha 1 chain, versican) as well as the genes SERPINE1 and PMEPA1, which are associated with epithelial-to-mesenchymal transition in various cancer types." (PMID 39695652, 2024). "However, the role of COL5A1 in other human cancers is still unidentified." (PMID 35082969, 2022). "Therefore, we hypothesized that high COL5A1 expression may lead to shorter survival time in these patients with advanced cancer." (PMID 35082969, 2022). "Based on our study, COL5A1 may be employed as a prognostic marker in different malignancies because of its impact on tumorigenesis and immune cell infiltration and have implications for cancer immune checkpoint inhibitors and chemotherapy." (PMID 35082969, 2022). "In this study, we developed a novel CAF-related prognostic model using data from the The Cancer Genome Atlas and Gene Expression Omnibus databases and identified SERPINH1 and COL5A1 as CAF-related genes in GBM." (PMID 40530702, 2025). "The COL5A1 is also reported as functionally prominent in the collagen hierarchy and fibers assembly in ECM and promoting proliferation and metastasis in cancers." (PMID 37504302, 2023). "Correlation between the COL1A1 or COL5A1 expressions and CAF infiltration was strong in all four cancers (rho > 0.5)." (PMID 35739492, 2022). "We further assessed the relationship between COL5A1 and the IC50 of chemotherapeutic drug usually used in these cancer types." (PMID 35082969, 2022). "Herein, we mainly used numerous silico analyses to discover the role of COL5A1 in the prognosis, TIIC infiltration, and drug sensitivity in 33 human cancers." (PMID 35082969, 2022). "We also examined correlations between expression of COL6A3, COL5A1, and COL8A1 with M1 and M2 macrophages in the seven selected types of cancer." (PMID 32523603, 2020). "Genes co-expressed with WISP1 were mainly associated with extracellular matrix organization, with collagen members COL6A3, COL5A1, and COL8A1 being key genes correlated with macrophage infiltration and M2 polarization in pan-cancer." (PMID 32523603, 2020). "Together, these results suggest that the collagen members COL6A3, COL5A1, and COL8A1 are key genes in the seven selected cancers, reflecting alterations in ECM organization." (PMID 32523603, 2020). "And the positively correlation between the infiltrating levels of macrophages and the expression of COL5A1, COL6A3, and COL8A1 were confirmed in diverse cancer types using CIBERSORT method." (PMID 32523603, 2020). "We next examined correlations between expression of the collagen members COL6A3, COL5A1, and COL8A1 and markers of macrophages in the seven selected cancer types in TIMER." (PMID 32523603, 2020). "In this study, we showed that COL6A3, COL5A1, and COL8A1 most likely be effector molecules of WISP1 and were positively correlated with monocyte infiltration and M2 polarization in pan-cancer." (PMID 32523603, 2020). "The genome-wide co-expression analyses showed that the expression levels of collagen genes (COL1A1, COL1A2, COL5A1, COL5A2, COL8A1 and COL8A2) and LincRNAs (Linc01614 and Linc01711) were significantly positively correlated with PODNL1 expressions in various cancers." (PMID 37504302, 2023). "These neighboring genes formed a ranked gene list based on their explained EMGNN contributions to the prediction of COL5A1 as a cancer gene or not." (PMID 37862225, 2023). "The DNA methylation of COL5A1 in other cancers was not significantly different from that in normal tissues." (PMID 35082969, 2022).
cancer (continued). "Although some evidence supports a significant role for COL5A1 in the progression of several cancers, a pan-cancer analysis of COL5A1 is not currently available." (PMID 35082969, 2022). "Our findings indicated that COL5A1 was expressed at high levels in 13 cancers and was negatively related to the prognosis of 11 cancers." (PMID 35082969, 2022). "Furthermore, H19 regulated many other cancer-related genes in this network, such as AKT3, CSF1, MET, COL1A1, COL5A1, WWTR1, EPHB4, and TMPRSS3." (PMID 31164794, 2019). "The prognostic predictive value of COL5A1 across cancers has not been adequately studied." (PMID 35082969, 2022). "Using the ChIP Seq bam files, we visualized the exact genomic location of DVL-1 binding (blue peak) at various cancer-associated genes not previously designated as Wnt target genes such as TRIO, COL5A1, EXD3, OR4A47, GLDN, and EFCAB6 compared to IgG control (red peak) using IGV." (PMID 34659647, 2021). "Interestingly, the function enrichment analysis of genes co-expressed with COL5A1 concluded a number of significant KEGG pathways and GO categories (p < 0.05) participating in the malignant behavior of proliferation, invasion, and migration in cancers." (PMID 34868960, 2021). "Also, enhanced monocyte-macrophage trafficking and M2 polarization are correlated with expression of collagen members COL6A3, COL5A1, and COL8A1, which may orchestrate the cancer-promoting effects of WISP1." (PMID 32523603, 2020). "However, no obvious correlation was observed between age and COL5A1 expression in other cancers." (PMID 35082969, 2022).
connective tissue disorder (24 papers, 2006 to 2025). A disease involving the connective tissue. "Mutations in COL5A1 are also closely associated with classical Ehlers–Danlos syndrome—a genetic connective tissue disorder marked by joint laxity and fragile tendons and ligaments." (PMID 40869983, 2025). "EDS (Classic Type) is a hereditary connective tissue disorder characterized by joint hypermobility, skin hyperextensibility, and tissue fragility due to mutations in the COL5A1 or COL5A2 genes encoding type V collagen." (PMID 40110250, 2025). "Classical Ehlers–Danlos syndrome (cEDS) is a connective tissue disorder mainly caused by heterozygous COL5A1 or COL5A2 variants encoding type V collagen and rarely by the p.(Arg312Cys) missense substitution in COL1A1 encoding type I collagen." (PMID 32720758, 2020). "For fCEAA, there were many connective tissue disorders (due to the collagen protein family), as well as several proteins linked to miscarriage (COL5A1, IGFBP6, LGALS3); for fEAA, proteins were linked to immunological disorders, primarily due to the chemokine family and their receptors." (PMID 39401228, 2024). "Haploinsufficiency of the COL5A1 gene, which encodes the proα1(V) chain of type V collagen, is the classical form of the Ehlers–Danlos syndrome, a connective tissue disorder characterized by skin hyperextensibility, atrophic scarring, and generalized joint hypermobility." (PMID 37174662, 2023). "Genetic screening for connective tissue diseases identified a heterozygous missense COL5A1 variant with unknown clinical significance." (PMID 35911880, 2022). "Genetic screening for connective tissue diseases identified a heterozygous missense collagen type V alpha 1 chain (COL5A1) variant with unknown clinical significance." (PMID 35911880, 2022). "Noteworthy, the mutations in COL5A1, COL6A1, or COL12A1 cause connective tissue disorders in humans, altering fiber organization and mechanical properties, resulting in tissue fragility." (PMID 34575162, 2021). "As outlined in the introduction, the type V collagen gene COL5A1 is a strong candidate for CCT, given the phenotypic association between the connective tissue disorder EDS and abnormal CCT values." (PMID 20485516, 2010). "COL5A1, an extracellular matrix (ECM) protein known to be involved in connective tissue disorders, has been identified in placental stromal cells and has been shown to be increased in PE placentas." (PMID 24963923, 2014).
infection (3 papers, 2018 to 2023). The state of being infected such as from the introduction of a foreign agent such as serum, vaccine, antigenic substance or organism. "Also, whereas collagen proteins were downregulated during infection of HFFF-TERTs, the same proteins were upregulated in THP-1s (COL1A1, COL1A2, COL3A1, COL5A1, and COL12A1)." (PMID 38065956, 2023).
adenocarcinoma (2 papers, 2023 to 2024). A common cancer characterized by the presence of malignant glandular cells. "Our research found that by inhibiting COL5A1, Sorafenib-treated myofibroblasts inhibited adenocarcinoma cells’ invasion ability and sensitized adenocarcinoma cells to cisplatin." (PMID 38987529, 2024). "COL5A1 knockdown in metastatic human adenocarcinoma cells also hindered cell growth and invasion and brought on apoptosis." (PMID 37476379, 2023).
benign tumor (1 paper, 2019). "The concentration of serum COL5A1 in IDC patients, the benign tumor patients, and the healthy controls was 40.42, 43.08, and 42.24 μg/L, respectively." (PMID 30982780, 2019).
metabolic disease (1 paper, 2025). A congenital disorder (due to inherited enzyme abnormality) or acquired (due to failure of a metabolically important organ) disorder resulting from an abnormal metabolic process. "For example, a study demonstrated that remodeling of the ECM in adipose and muscle tissue plays a pivotal role in metabolic disease development, identifying genes such as TCF7L2, ADIPOQ, CD36, PPARG, IL6, SIRT1, and COL5A1 as key regulators of inflammation." (PMID 41303617, 2025).
COL5A1 also shares sentences with these, for which no sentence is quoted: clear cell renal cell carcinoma (5 papers); colorectal cancer (3); breast invasive carcinoma (2); carpal tunnel syndrome (2); cerebrovascular disease (2); esophageal squamous cell carcinoma (2); head and neck squamous cell carcinoma (2); pancreatic adenocarcinoma (2); pulmonary fibrosis (2); rotator cuff tear (2); tongue squamous cell carcinoma (2); abdominal aortic aneurysm (1); acute myeloid leukemia (1); adrenocortical carcinoma (1); ameloblastoma (1); angina (1); aortic aneurysm (1); arachnodactyly (1); arterial disease (1); autosomal recessive intellectual disability (1); bladder tumors (1); bladder urothelial carcinoma (1); cholangiocarcinoma (1); chondrosarcoma (1); CNS tumors (1); colitis (1); corneal dystrophy (1); cutaneous melanoma (1); dermatosparaxis (1); diabetic nephropathy (1).
A further 58 diseases each share a sentence with COL5A1 in 1 paper.